LGALS1 (galectin 1)
Diseases named in the same sentence as LGALS1 in open-access papers (continued):
Sharing a sentence is not in itself a finding about the gene and the disease.
breast cancer (continued). "Galectin-1 is upregulated in breast carcinoma tissues and is clinically significant in patients with breast cancer." (PMID 39996781, 2025). "Subgroup analyses showed significantly lower survival rates in the patients with high galectin-1 expression in the luminal B and basal types of breast cancer." (PMID 39996781, 2025). "Cell experiments showed that miR-22-3p overexpression and galectin-1 knockdown inhibited the proliferation and invasion of breast cancer cells." (PMID 39996781, 2025). "In our study, miR-22-3p overexpression and galectin-1 knockdown suppressed the growth and invasion of breast cancer cells." (PMID 39996781, 2025). "The purpose of this study is to identify the clinical significance and biological role of galectin-1 and miR-22-3p in cancer progression according to the molecular subtype of breast cancer." (PMID 39996781, 2025). "Galectin-1 has been studied as a therapeutic target in various types of cancer, including prostate, thyroid, colon, melanoma, bladder, ovarian, and breast cancers." (PMID 39996781, 2025). "For example, galectin-1 levels in breast cancer have been shown to increase after treatment that included chemotherapy, hormonal therapy, and immunotherapy." (PMID 38539500, 2024). "According to the literature, SUSD2 interacts with Galectin-1, facilitating tumor immune evasion, angiogenesis, and metastasis in breast cancer." (PMID 39247587, 2024). "Thiodigalactoside, a carbohydrate-based galectin-1 inhibitor, has been shown to prevent angiogenesis and tumor growth while preventing metastasis and inducing the apoptosis of tumor cells in breast cancer samples in tumor mouse models." (PMID 38927753, 2024). "Galectin-1 is highly expressed in numerous cancers, such as lung cancer, breast cancer, pancreatic cancer, and ovarian cancer." (PMID 37433225, 2023). "They discovered that gain-of-function mutations in the KIT proto-oncogene are consistently associated with elevated serum levels of galectins -1, -3, -8, and -9 in breast cancer and galectin-1 in non-small cell lung cancer patients." (PMID 36817445, 2023). "In ovarian and breast cancers, IL-6-induced systemic inflammation enhances the mobilization of myeloid-derived suppressor cells which primed ɣδ T cells to produce galectin-1, thereby abolishing anti-tumor immunity." (PMID 36873388, 2023). "Nanoparticles of Anginex were used in a galectin-1-overexpressing breast cancer mouse model, showing a robust reduction in tumor growth, and similar results were obtained with Anginex analogues (6DBF7, DB16, DB21)." (PMID 36873388, 2023). "The heatmap showed that the HMGA1-high cluster expressed TMSB10, CTSD and LGALS1, which are correlated with poor prognosis in breast cancer." (PMID 35611554, 2022). "The Sushi Domain Containing 2 (SUSD2) is a cell membrane protein with adhesion domains that interacts with Galectin-1 to promote breast cancer immune evasion, angiogenesis, invasion and metastasis." (PMID 36038558, 2022). "In breast cancer, a connection between diverse galectin expression patterns and different cancer characteristics—like a correlation of galectin-1 (Gal-1) expression with tumor grading—was found." (PMID 32290551, 2020). "Meanwhile, another study found that nuclear localization of Galectin-1 regulates mammary morphogenesis and promotes breast cancer progression by up-regulation of Erk1/2 expression." (PMID 31492191, 2019). "This has been reported in A498 and breast cancer cell lines, as well as in normal lymphatic endothelial cells, where endogenous Galectin-1 regulates migration through different mechanisms." (PMID 29580262, 2018). "To confirm this relationship, we analyzed galectin-1 expression in breast cancer tissue specimens by western blotting." (PMID 28415760, 2017). "To determine the effect of galectin-1 silencing on the drug sensitivity of human breast cancer cells, we induced apoptosis by treatment with doxorubicin, which damages cellular DNA." (PMID 28415760, 2017).
breast cancer (continued). "Based on our finding that galectin-1 ablation inhibited survivin expression in human breast cancer cells, we investigated the mechanism by which galectin-1 promotes survivin expression." (PMID 28415760, 2017). "Treatment of breast cancer tumor cells with galectin-1 leads to reduced cell binding to laminin and plasma or placental fibronectin." (PMID 27825375, 2016). "Galectin-1 expression has been identified as a signature of cellular invasiveness of mammary carcinoma cell." (PMID 27649167, 2016). "Accordingly, silencing of galectin-1 in breast carcinoma model inhibited tumor growth and prevented metastatic disease." (PMID 26006245, 2015). "Silencing of Galectin-1 in a metastatic murine mammary tumor led to a reduction of tumor growth and lung metastasis with a concomitant reduction in infiltrating regulatory T-cells." (PMID 24592356, 2014). "In another study, the amount of Galectin-1 positive cells correlated with the tumor grade in human breast cancer." (PMID 24592356, 2014). "Moreover, Western blotting and quantitative immunofluorescence in three breast cancer cell lines confirmed that PD-L1 is an upstream regulator of Livin, Galectin-1, and SKP2 protein expression." (PMID 41898602, 2026). "The expression levels of galectin-1 and miR-22-3p varied across different breast cancer cell lines." (PMID 39996781, 2025). "Galectin-1 is known to play an oncogenic role in breast cancer progression." (PMID 39996781, 2025). "The galectin-1 expression levels were significantly associated with OS and RFS in breast cancer." (PMID 39996781, 2025). "In addition, it was confirmed that miR-22-3p inhibits breast cancer growth by inhibiting galectin-1; however, it is estimated that miR-22-3p itself serves as a tumor suppressor through several targets." (PMID 39996781, 2025). "In addition, we investigated the regulation of the cell cycle and EMT processes of cancer progression through the galectin-1/miR-22-3p axis using cell lines of different breast cancer subtypes." (PMID 39996781, 2025). "It has also been reported that galectin-1 regulates cell growth and metastasis in breast cancer." (PMID 39996781, 2025). "Upon investigating the mammary tumor tissue from docetaxel-treated mice, we found an increase in protumor immune infiltrates including M2 macrophages, MDSCs, Tregs, γδT cells, and an enriched gene signature comprising Vim, Spp1, S100a6, Ccl2, and Lgals1 genes." (PMID 37699010, 2023). "Galectin-1 expression is elevated in highly metastatic human breast tumors and has been shown to be correlated with poor prognosis in patients with aggressive breast cancer." (PMID 28415760, 2017). "Based on previous work demonstrating that galectin-1 can activate cell migration and invasion in various cancer cell lines, we investigated the effect of galectin-1 knock-down on the migration and invasion of human breast cancer cells." (PMID 28415760, 2017). "Also Galectin-1 was found bound to Hpt glycoforms, that were present at increased levels in sera of patients with breast cancer." (PMID 23272204, 2012). "In conclusion, the miR-22-3p/galectin-1 axis regulates different cancer metastasis mechanisms depending on the specific molecular subtype of breast cancer, and miR-22-3p/galectin-1 axis modulation may be a novel target for molecular subtype-specific personalized treatment." (PMID 39996781, 2025). "Changes in cell cycle-related proteins caused by galectin-1 knockdown in the MDA-MB231 cells were relatively minimal, except for a slight decrease in cyclins A and D (p < 0.05) indicating that cell cycle regulation was prominent in the T47D cells, a hormone receptor-positive breast cancer cell line." (PMID 39996781, 2025). "Inhibition of LGALS1 has been shown to reduce the metastatic capability of the MDA-MB-231 breast cancer cell line, and expression of LGALS1 can affect the metastasis of breast cancer, supporting our hypothesis that targeting LGALS1 could obstruct tumor progression." (PMID 37475016, 2023).
breast cancer (continued). "Likewise, the chemokine receptor CXCR4 has multiple upstream mediators, with upregulation in renal cell carcinoma described in response to hypoxia inducible factor (HIF1a) and galectin 1, and in breast cancer with angiotensin II type I receptor (AGTR-1) and NF kappa B." (PMID 33927349, 2021). "SUSD2′s pathogenicity in breast cancer may be mediated through Galectin-1 (Gal-1)." (PMID 31387209, 2019). "Therefore to evaluate the putative relevance galectin-1 and the ligation of the TF epitope could have in breast cancer treatment regimes, testing in heterotypic spheroid models could provide further information." (PMID 27825375, 2016). "Conversely, other studies have shown that galectin-1 inhibits cell proliferation and metabolic activity, and induces apoptosis in MCF-7 breast cancer cells." (PMID 39996781, 2025). "For BCSC-immune cell cross-talk, LGALS1-PTPRC, NECTIN2-CD96, and NECTIN2/4-TIGIT are found to hamper immunity against breast cancer; by expressing TIMP-1, BCSC promotes epithelial-mesenchymal transition (EMT) by interacting with CD63 in epithelial cells." (PMID 34611125, 2021). "In this study we examined the impact galectin-1 has in vitro on cell proliferation, apoptotic potential and metabolic activity of MCF-7 and T-47D breast cancer cells in dependence to their expression of the Thomsen-Friedenreich (TF) tumor antigen." (PMID 27825375, 2016). "Furthermore, the downregulation of galectin-1 functions as a tumor suppressor, influencing the cell cycle and EMT pathways in breast cancer to mitigate tumor progression." (PMID 39996781, 2025). "Increased binding potential for galectin-1 in breast cancer cells seems to correlate with a positive lymph node status and with tumor size and stage, whereas the presence of galectin-1 was identified as a factor that correlates with a lack of metastatic lesions in lymph nodes." (PMID 27825375, 2016). "Galectin-1 expression was higher in the T47D and MDA-MB 231 cells than in the other breast cancer cell lines and in the non-tumor epithelial cell line." (PMID 39996781, 2025).
pancreatic cancer (31 papers, 2009 to 2025). "Stromal-derived Galectin-1 has been associated with vascularization and metastasis formation in pancreatic cancer, proving to be a good candidate for therapeutic targeting." (PMID 38384845, 2024). "Galectin-1 expression in pancreatic cancer demonstrates a significant association with the disease’s progression and metastasis, particularly in lymph node metastases." (PMID 37958483, 2023). "Furthermore, pancreatic cancer tumors in mice with galectin-1 deficiency exhibited abnormalities in the stroma related to the Hh signaling pathway." (PMID 36428567, 2022). "Galectin-1 has been implicated in the regulation of cell adhesion, migration, and cell growth in a wide variety of cell types, including activated T cells, vascular smooth muscle, neuroblastoma, and pancreatic carcinoma cells." (PMID 19898636, 2009). "Recent preclinical studies have identified a novel role for Galectin-1 in pancreatic cancer, acting not only as an extracellular signaling molecule but also as a nuclear regulator that sustains KRAS expression in cancer-associated fibroblasts." (PMID 40806185, 2025). "Galectin-1 has gained prominence as a significant prognostic factor in pancreatic cancer, with various facets of its expression shedding light on patient outcomes." (PMID 37958483, 2023). "Galectin-1’s role in enhancing the migratory potential of pancreatic cancer cells, particularly through the modulation of stromal cell-derived factor-1 (SDF-1), has been delineated." (PMID 37958483, 2023). "Stromal-derived galectin-1, can even contribute to pancreatic cancer progression and represents an interesting target for anti-tumour therapies." (PMID 35017635, 2022). "In pancreatic cancer, galectin-1 promotes the secretion of matrix metalloproteinase (MMP9) and IDO, and high expression of MMP9 and IDO can result in NK cell dysfunction." (PMID 36428567, 2022). "In contrast to galectin-1, the galectin-3 helps pancreatic tumor cells to participate in immune evasion mainly by interacting with the immune cells." (PMID 36428567, 2022). "In silico analysis reveals that LGALS1 is overexpressed in various tumours including glioblastoma and pancreatic carcinoma." (PMID 35632759, 2022). "Trials on pancreatic cancer revealed that depleted expression of LGALS1 leads to impaired vascularization of the tumor tissue, and restored T-cell immunity." (PMID 34611125, 2021). "Galectin-1 also reportedly enhances the production of stromal cell-derived factor-1via NF-κB signalling, resulting in increased metastasis in pancreatic cancer both in vitro and in vivo." (PMID 31832021, 2019). "Taken together, our results suggest that high expression of galectin-1 and low levels of galectin-4 or galectin-9 are predictors of worse prognosis in pancreatic cancer patients." (PMID 31832021, 2019). "Galectin-1 promotes immunosuppression in the pancreatic cancer microenvironment by inducing T cell apoptosis and Th2 cytokine secretion." (PMID 30060755, 2018). "Previous studies have shown that overexpression of Galectin-1 in PSCs induced T cell apoptosis, anergy, and Th2 cytokine secretion, and promoted the proliferation, invasion, and metastasis of pancreatic cancer cells." (PMID 29156810, 2017). "In particular, PSC-derived overexpression of Galectin-1 promoted the invasion and metastasis of pancreatic cancer cells into the wall of the stomach and liver by inducing EMT." (PMID 29156810, 2017). "In this study, we examined the effects of Galectin-1 knockdown or overexpression in PSCs co-cultured with pancreatic cancer (PANC-1) cells." (PMID 29156810, 2017). "We evaluated the effect of PSC-derived Galectin-1 on the proliferation of the pancreatic cancer cell line, PANC-1." (PMID 29156810, 2017). "Our previous studies have shown Galectin-1 expression in PSCs increases with the degree of malignancy of pancreatic cancer." (PMID 29156810, 2017).
pancreatic cancer (continued). "PSC-derived Galectin-1 promoted the proliferation, invasion, and survival of a pancreatic cancer cell line (PANC-1)." (PMID 29156810, 2017). "For this purpose eight human pancreatic cancer cell (PaCa) lines were tested for the expression of galectin-1 at the mRNA and protein levels." (PMID 27993133, 2016). "In PDAC group, Galectin-1 expression was mainly detected in the stromal cells of all the pancreatic cancer." (PMID 24595374, 2014). "In conclusion, our findings supported that expression of Galectin-1 inPSCs was related with tumor invasiveness and progression as well as with short patient survival in pancreatic cancer." (PMID 24595374, 2014). "Univariate and multivariate analysis of conventional prognostic factors and stromal galectin-1 expression in the patients with pancreatic cancer." (PMID 24595374, 2014). "In order to further confirm the role of PSCs derived Galectin-1 on pancreatic cancer progression, we isolated PSCs from pancreatic cancer tissues (hCaPSCs) and normal pancreatic tissue (hNPSC), respectively." (PMID 24595374, 2014). "Galectin-1 was expressed in the activated PSCs which were the source of fibroblasts around pancreatic cancer cells, and have a role in chemokine production and proliferation through its beta-galactoside binding activity in activated PSCs." (PMID 24595374, 2014). "More important, Galectin-1 was strong expressed in pancreatic cancer, of which Galectin-1 expression was closely related to tumor size, perineural invasion, tumor stage, differentiation and poor prognosis." (PMID 24595374, 2014). "Galectin-1 expression in stromal cells of pancreatic cancer suggests that this protein plays a role in the promotion of cancer cells invasion and metastasis and provides a therapeutic target for the treatment of pancreatic cancer." (PMID 24595374, 2014). "Galectin-1 intensity of staining and clinicopathologic characteristics of the 18 patients with chronic pancreatitis and 66 patients with pancreatic cancer." (PMID 24595374, 2014). "Northern blotting and Western blotting analysis showed significantly higher galectin-1 and galectin-3 mRNA and protein levels in pancreatic cancer samples compared to normal controls." (PMID 23658855, 2010). "Taken together the expression pattern of galectin-1 and galectin-3 in pancreatic cancer tissues indicates that these proteins can be useful biomarkers in this type of cancer." (PMID 23658855, 2010). "Furthermore, they play a crucial role in the pancreatic cancer environment by releasing factors like SDF-1, HGF, galectin-1, TGFβ, and IL-6, promoting pancreatic cancer progression." (PMID 39199647, 2024). "A high Galectin-1 level promotes pancreatic cancer cell proliferation and tumor metastasis." (PMID 37433225, 2023). "Recognizing the diverse roles of Galectin-1 could potentially unlock new therapeutic avenues to combat this aggressive cancer, especially given its impact on pancreatic cancer cell migration, fibrosis, and the epithelial–mesenchymal transition (EMT)." (PMID 37958483, 2023). "Galectin-1 breaks the Th1/2 balance in pancreatic cancer, and the over-expression of galectin-1 in PSC may enhance the release of IL-5, thus, enhancing the tumor fibrosis." (PMID 36428567, 2022). "The current review study identifies 22 IHC biomarkers as diagnostic tools for pancreatic cancer that embrace: Pentraxin-3, ENO1, REG4, POSTN, CA125, CA242, Galectin-1, Galectin-9, Maspin, pVHL, MUC1, MUC5AC, THBS2, LTBP2, CPA4, IMP3, CD13, Dkk1, KOC, S100P, Mesothelin, PAM4." (PMID 34988027, 2021). "Galectin-1 has also been proved to play oncogenic role by some researches in pancreatic cancer." (PMID 31832021, 2019). "In addition, a novel galectin-1 inhibitor LLS2 was found to potentiate the antitumor effects of paclitaxel in several human cancer cell lines including pancreatic cancer cells in vitro." (PMID 31832021, 2019).